TNF (tumor necrosis factor)
Diseases named in the same sentence as TNF in open-access papers (continued):
Sharing a sentence is not in itself a finding about the gene and the disease.
ischemic stroke (394 papers, 2008 to 2026). A stroke disorder caused by obstruction of blood flow to the brain, due to thrombotic (local blood clot formation) or embolic (due to a blood clot or other material traveling from another site) event. "Increasing levels of TNF-α have demonstrated increased risk of coronary artery disease (OR 2.25, 95% CI: 1.50–3.37) and ischemic stroke (OR 2.27, 95%CI: 1.50–3.43)." (PMID 40278353, 2025). "A meta-analysis further linked elevated TNF-α with reduced IGF-1 as joint risk factors for ischemic stroke." (PMID 41393761, 2025). "Polymorphisms in the TNF gene and persistently elevated TNF-α are associated with increased susceptibility to ischemic stroke in multiple populations." (PMID 40869247, 2025). "Elevated levels of IL-6 and TNF-alpha during the acute phase of ischemic stroke have been strongly associated with more severe initial disability." (PMID 39859987, 2025). "Treatment of ADA2 deficiency involves anti-tumor necrosis factor alpha agents, which prevent and eliminate manifestations of autoinflammatory disease, reduce the risk of ischemic stroke, and relieve immunodeficiency." (PMID 41362886, 2025). "Inflammation is a potential cause of ischemic stroke, and DNA methylation and histone acetylation alter the promoter region of TNF-α." (PMID 37728582, 2024). "The pro-inflammatory cytokines are also the key mediators of BBB damage in ischemic stroke, since intracerebral administration of TNF-α will cause BBB breakdown." (PMID 36782269, 2023). "Previous studies reported that IL-1, which increased after ischaemic stroke or other risk factors, targeted astrocytes and increased the expression of IL-6, TNF-a, MMP-9, and chemokines." (PMID 36600830, 2023). "Demonstrating a causal role of this molecule in ischemic stroke pathophysiology in humans, specific TNF-α polymorphisms have been associated with higher risk of ischemic stroke." (PMID 36745280, 2023). "Using NR4A1 global knockout mice, Liu and colleagues further demonstrate that loss of NR4A1 leads to increased TNF expression and worse outcomes in a mouse model of ischemic stroke." (PMID 37490433, 2023). "A recent bioinformatic study revealed that among key immunoregulatory pathways implicated in ischemic stroke pathogenesis, TNF-related signaling covers a pivotal role." (PMID 36674674, 2023). "Tumor necrosis factor (TNF) is a potent inflammatory cytokine that has been causally associated with coronary artery disease (CAD) and ischemic stroke (IS), implying opportunities for disease prevention by anti-TNF therapeutics." (PMID 35074627, 2022). "Patient prognosis is associated with TNF-α gene polymorphism; therefore, TNF-α inhibition should be considered in the treatment of ischemic stroke." (PMID 36211352, 2022). "Our findings suggest a close association of PABPC1, PFDN5, and TNF with female ischemic stroke patients." (PMID 35432523, 2022). "Ischemic stroke injury can activate astrocytes, causing them to produce and release excessive amounts of TNF-α." (PMID 35781632, 2022). "The causal effect of tumor necrosis factor on coronary artery disease and ischemic stroke, was recently reported by a Mendelian randomization study as well." (PMID 35074627, 2022). "Patients with ischemic stroke have increased TNF-α serum levels and higher risk for cardiovascular diseases, compared with healthy volunteers." (PMID 34084749, 2021). "Apart from ER stress, RNA-seq also suggested that the mechanism by which γ-GC alleviates ischemic stroke is associated with ferroptosis and the TNF signaling pathway." (PMID 34824669, 2021). "The study of neurological diseases has found that DNTs lay a pro-inflammatory effect by promoting the activation of microglia in mice with ischemic stroke, which is associated with the secretion of TNF-α." (PMID 34491906, 2021). "In the pathology of ischemic stroke, TNFα and IL6 appear to be associated with BBB damage as seen on enhanced magnetic resonance imaging (MRI) scans." (PMID 32432126, 2020).
ischemic stroke (continued). "For instance, SC downregulated the levels of proinflammatory factors (TNF-α, IL-1β, and IL-6), while upregulated the activities of antioxidant enzymes in cardiomyocyte hypoxia; a complication usually occurs associated with ischemic stroke." (PMID 32240450, 2020). "In the present MR study, we provided the first causal evidence of positive associations of TNF levels with atherothrombotic disease (coronary artery disease and ischaemic stroke) and venous thromboembolism." (PMID 32805626, 2020). "TNF-α and IL-1β are risk factors for ischemic stroke in humans and result in neurotoxicity in rats after an ischemic event." (PMID 30237808, 2018). "TNF inhibitors have been the only proven effective therapy for the prevention of DADA2-associated ischemic strokes." (PMID 29963054, 2018). "Classically, three pro-inflammatory cytokines, IL-1β, IL-6, and TNFα are associated with the inflammatory response following ischemic stroke." (PMID 29426336, 2018). "The pro-inflammatory cytokines IL-1β and TNF-α have been implicated as key contributors to ischemic stroke and reperfusion." (PMID 28769792, 2017). "Prior atorvastatin treatment in patients with ischemic stroke was associated with a lower concentration of IL-6 and TNF-α and improved the outcome of VAP." (PMID 28357403, 2017). "Previous studies showed several interleukins (IL1, IL6, IL8, TNF, etc.)play a crucial role in immune processes and strongly associated with ischemic stroke." (PMID 27672514, 2016). "miR-146a also regulates the expression level of TNF-α, which is associated with the occurrence of ischemic stroke." (PMID 25658319, 2015). "We demonstrate elevated serum TNF-α level was associated with higher risk of ischemic stroke in the Chinese Han population." (PMID 23050663, 2012). "In particular, TNF-α and IL-6 are related to the risk of recurrent ischemic stroke independently of conventional risk markers." (PMID 20700422, 2010). "After ischemic stroke, the proinflammatory process causes injured neurons and glial cells to produce cytokines, such as TNF-α or IL-1, resulting in increased production and release of EC adhesion molecules (including ICAM-1, VCAM-1, E-selectin, and P-selectin)." (PMID 39707228, 2024). "Additionally, the KEGG pathways associated with PA in ischemic stroke were mainly related to the TNF signaling pathway, IL-17 signaling pathway, and HIF-1 signaling pathway." (PMID 38448479, 2024). "Furthermore, a randomized controlled study of ischemic stroke patients demonstrated that tumor necrosis factor-α and the interleukins (IL), such as IL-1β, IL-6, and IL-20, were associated with inflammation in ischemic stroke." (PMID 37533068, 2023). "Therefore, in the present study, we investigated the effect of minocycline on selected proteins implicated in the inflammatory response after ischemic stroke, including TNFα, HSP70, and the RNA-binding protein HuR." (PMID 37298395, 2023). "The protection against ischemic stroke symptoms was associated with the reduced tumor necrosis factor-α, interleukin-1β, superoxide, and lipid peroxide levels, promoting superoxide dismutase activity in the hippocampus in the CSW groups, compared to the I/R-control." (PMID 35052672, 2022). "However, it should be considered that TNF-α and IL-6 also play a role in protecting the brain parenchyma against damage caused by ischemic stroke in the subsequent ischemic stages." (PMID 36142524, 2022). "Studies have shown that the level of TNF-α was elevated in ischemic stroke and it has been implicated in cerebral I/R injury, exerting effects by regulating the inflammatory response and PCD pathways including apoptosis, necroptosis, and pyroptosis, which is consistent with our results." (PMID 35991562, 2022). "In addition, previous epidemiological studies demonstrated that higher serum TNF-α concentrations were related to higher risk of ischemic stroke and recurrent coronary events." (PMID 33839698, 2021).
ischemic stroke (continued). "Atorvastatin could decrease the concentration of IL-6 and TNF-α and improved the outcome of ventilator-associated pneumonia in patients with ischemic stroke." (PMID 33728336, 2021). "Increased levels of TNF-α have previously been associated with poor outcome after ischemic stroke." (PMID 33578805, 2021). "A possible positive association of TNF with ischaemic stroke has been reported." (PMID 32805626, 2020). "There was weak evidence of association between TNF levels and ischaemic stroke in UK Biobank." (PMID 32805626, 2020). "Control of inflammation through blockade of TNF may lead to a reduction in the risk of ischemic stroke." (PMID 26749043, 2016). "Tumor necrosis factor inhibitors (TNFi) may influence risk and mortality after ischemic stroke by reducing inflammation." (PMID 26749043, 2016). "Compared with the vehicle-treated rats, the PJ34-treated rats had more severe neuronal deficits and a larger infarct volume and exhibited fewer activated microglia, greater neuronal loss, decreased GDNF expression and increased TNF-α expression at 3 and 7 days following ischemic stroke." (PMID 23151666, 2013). "Interestingly, the rs1800629 polymorphism, which might boost TNF gene transcriptional activity, associated with increased TNF-plasma levels in ischemic stroke etiology, and this result was confirmed by genetic association data analysis." (PMID 36622512, 2023). "Ischemic stroke is a result of an occlusion of one or more blood vessels that lead to an instantaneous loss of oxygen from the cerebral tissue, which activates microglial cells that, in turn, induce the secretion of a large number of inflammatory cytokines (TNFα, IL-1β, IL-6)." (PMID 30208640, 2018). "A comprehensive analysis of current evidence underscores the central, temporally and contextually dependent role of TNF-α in the pathophysiology of ischemic stroke." (PMID 41683844, 2026). "During ischemic stroke, microglia produce pro-inflammatory cytokines such as tumor necrosis factor (TNF), interleukin 1 beta (IL1β), interleukin 6 (IL6), and proteolytic enzymes such as matrix metalloproteinase 9 (MMP9)." (PMID 40676515, 2025). "By down-regulating the TLR, suppress the activation of NF-κB and block the signal from being sent to the downstream factor TNF-α, in order to resist immune cell infiltration and relieve ischemic stroke." (PMID 40756985, 2025). "This resulted in reduced infarct size and neuroinflammation (iNOS/Arg1, TNF-α, and IL-1β levels) after ischemic stroke." (PMID 40867911, 2025). "In ischemic stroke models, butyrate produced by C. butyricum inhibits excessive microglial activation via Akt phosphorylation, downregulates hippocampal TNF-α/IL-1β levels, and reduces infarct volume." (PMID 40895486, 2025). "TNFα is a pro-inflammatory cytokine that is rapidly upregulated in the brain following ischemic stroke and promotes the recruitment of immune cells to the site of injury." (PMID 40362325, 2025). "In a mouse model of middle cerebral artery occlusion (MCAO), M1-type microglia significantly exacerbated vascular endothelial injury and blood-brain barrier (BBB) disruption after ischemic stroke by secreting the pro-inflammatory factor TNF-α." (PMID 41451205, 2025). "Silencing HDAC9 has been shown to reduce infarct size, suppress pro-inflammatory cytokine expression (e.g., IL-1β, TNF-α, IL-6), and improve neurological function, underscoring its potential as a therapeutic target in ischemic stroke." (PMID 40867911, 2025). "In ischemic stroke-induced neuroinflammation, IL-1β, IL-6 and TNF-α are three pro-inflammatory cytokines." (PMID 40004043, 2025). "Cytokines play a pivotal role in the inflammatory response following an ischemic stroke with TNF-α, IL-1β, IL-6, and IL-10 being particularly significant." (PMID 40095189, 2025). "TNF-α exhibits a time-dependent and biphasic regulatory role in the pathogenesis of ischemic stroke." (PMID 41451205, 2025).
ischemic stroke (continued). "In ischemic stroke, microglia polarize into distinct phenotypes: pro-inflammatory M1 (secreting TNF-α, IL-1β, IL-6) and pro-angiogenic M2 (releasing IL-10, TGF-β, VEGF)." (PMID 40988927, 2025). "ELISA results revealed significant increases in the pro-inflammatory cytokines TNF-α, IL-1β, and IL-6 in brain tissue after ischemic stroke." (PMID 40400029, 2025). "Tumor necrosis factor alpha (TNF-α) is an extensively studied proinflammatory cytokine in ischemic stroke and a critical mediator of neuroinflammatory responses." (PMID 40943626, 2025). "Beyond IL-1β and TNF-α, numerous other cytokines play significant roles in the pathological progression of ischemic stroke." (PMID 41451205, 2025). "For example, reversing dysbiosis through the ingestion notoginseng saponins restored BBB integrity via increased occludin and Zo1 expression, and reduced proinflammatory cytokine expression (IL-1B, IL-6, TNF) in a rodent model of ischemic stroke." (PMID 40485663, 2025). "In ischemic stroke rats, neutrophil-derived IL-1α/TNF induce Aquaporin-4 polarization to perivascular astrocyte end-feet, disrupting water homeostasis." (PMID 40510212, 2025). "In a meta-analysis of publications on R. rosea efficacy in ischemic stroke, preclinical data proved its ameliorating effect on neuroinflammation (significant decrease in TNF-α)." (PMID 38398618, 2024). "Clinical studies have associated oxidative stress and pro-inflammatory cytokines such as IL-1β, IL-6, and TNF-α with poor outcomes in ischemic stroke patients." (PMID 39596503, 2024). "The regulating effect of inflammatory cytokines (TNF-α, IL-6, IL-10) in neuroinflammation accompanying induced ischemic stroke in rats was, moreover, demonstrated in an earlier study." (PMID 38398618, 2024). "Microglia are polarized to M1 subtype within a short period of time after ischemic stroke, thereby secreting various pro-inflammatory factors, including IL-1β, IL-6, IL-18 and TNF-α." (PMID 38421829, 2024). "Considering the pivotal role of TNF-α among key targets and its significance in ischemic stroke pathology, we subsequently delved into examining the changes in protein expression levels." (PMID 39771032, 2024). "Regarding TNF-α, the level was 690.0 ± 13.4 pg/ml in the Sham group, escalating significantly to 905.5 ± 16.4 pg/ml following ischemic stroke injury." (PMID 39628470, 2024). "Interleukins such as TNF-α, IL-2, IL-4, IL-6 and IL-10, secreted by lymphocytes, play an important role in the pathogenesis and prognosis of ischemic stroke." (PMID 39204113, 2024). "Ischemic stroke increases the release of TNF-α and IL-1β, which influence the severity of neurological deficits and cell damage through the production of free radicals." (PMID 38527023, 2024). "In ischemic stroke, activated microglia play a pivotal role in the initial immune -producing proinflammatory cytokines such as TNF-α and nitric oxide that ultimately contribute to the release of free radicals and mitochondrial damage." (PMID 38442272, 2024). "This serves as a determinant for the onset of inflammation in ischemic stroke, subsequently upregulating target genes, including IL-1β and TNF-α." (PMID 39062789, 2024). "Microglial activation exacerbates cerebral tissue damage in ischemic stroke by leading to the release of pro-inflammatory cytokines such as interleukin-1 beta (IL-1β), IL-6, and tumor necrosis factor-alpha (TNF-α)." (PMID 39057078, 2024). "This study found a downward trend in BMAL1 and SIRT1 expression along with increased activation of oxidative stress (MDA) and inflammatory factors (IL-6, TNF-α) in patients with early-onset ischemic stroke." (PMID 38245621, 2024). "In a mouse model of ischemic stroke, pretreatment with TwX (20 mg/kg/d) for 14 days not only reduced infarct size but also decreased the expression of OS markers and tumor necrosis factor-α (TNF-α) and inflammation markers." (PMID 38474309, 2024).
ischemic stroke (continued). "We examined the expression levels of the antioxidant stress kinase SOD and TNF-α at different onset times of ischaemic stroke and found that their expression levels were consistent with those of SIRT1-BMAL1." (PMID 38245621, 2024). "THSWD also inhibited the levels of tumor necrosis factor-α (TNF-α)(P < 0.01) and interleukin − 1β (IL-1β)(P < 0.01) in brain tissue, and increased alpha and beta diversity in ischemic stroke mice, along with a certain reversal effect on different microflora." (PMID 38500092, 2024). "We observed that PTS protected against neuronal damage and suppressed ischaemic stroke-induced changes in the levels of TNF-α, IL-1β and iNOS." (PMID 39198723, 2024). "In ischemic stroke models, TNFα has a pro-inflammatory effect in the acute phase but protective effects in later stages, as seen in hippocampal tissue." (PMID 39624169, 2024). "Within minutes after ischemic stroke, microglia are activated in an M1-like phenotype and release pro-inflammatory mediators, such as IL-6, TNF-α, iNOS, ROS, leading to the break of the BBB." (PMID 38879549, 2024). "This contributes to a reduction in infarct volume and neuroinflammation (iNOS/Arg1, TNF-α, and IL-1β levels) after ischaemic stroke, and Nrf1 acetylation plays a crucial role in this process." (PMID 39198723, 2024). "In an ischemic stroke, pro-inflammatory cytokines, containing IL-1β, IL-6, and TNF-α, are released from glial cells and/or neurons and trigger the inflammation." (PMID 38421829, 2024). "In animal models of ischemic stroke, cytokines were upregulated, which triggered proinflammatory (e.g., interleukin [IL]-1β, tumor necrosis factor [TNF], and IL-6) and anti-inflammatory (transforming growth factor-β and IL-10) mechanisms." (PMID 38206990, 2024). "In the case of ischemic stroke, a large number of cytokines, such as tumor necrosis factor-alpha (TNF-α) and interleukin-1 (IL-1), are released by cells surrounding the ischemic area." (PMID 38742047, 2024). "Ischemic stroke induces activation of NF-κB, overproduction of inflammatory factors such as TNF-α and IL-1β, activation of caspase proteins, and induction of neuronal cell death." (PMID 38527023, 2024). "Lymphocyte trafficking across blood-choroid plexus barrier has been reported in various conditions, including ischemic stroke, feline immunodeficiency virus infection and ventricular injection of tumor necrosis factor-alpha." (PMID 38654318, 2024). "During ischemic stroke, astrocytes become reactive and produce several proinflammatory cytokines, such as TNF-α, IL-1β, IL-6, and IFN-γ, in response to ischemia." (PMID 39707228, 2024). "Similar to the NR4A1 global knockout mice, loss of NR4A1 in microglia specifically results in increased TNF expression and aggravated outcomes after ischemic stroke." (PMID 37490433, 2023). "Intriguingly, TNF-α mRNA levels are elevated in circulating monocytes isolated from ischemic stroke patients 24–48 h after symptoms onset, and both TNFR1 and TNFR2 are differentially regulated in distinct subpopulations of monocytes and neutrophils." (PMID 36674674, 2023). "The NIHSS score, infarct volume and the levels of NLRP1, IL-6, TNF-α, and IL-1β of ischemic stroke patients in the mRS score ≥ 3 group were remarkably elevated than the ischemic stroke patients in the mRS score ≤ 2 group (P < .05)." (PMID 37000063, 2023). "Several substances have been found in the cerebrospinal fluid (CSF) of stroke patients, and studies suggest that TNF-α and IL-1β initiate neuroinflammation in ischemic stroke." (PMID 37840921, 2023). "Microglia are known to be the primary source of TNF-α in the early stages of acute ischemic stroke in both rodents and humans." (PMID 36890539, 2023). "Using double labeling with TNFα and the neuronal marker NeuN, we were observed TNFα expression in neurons as early as 12 h after the induction of ischemic stroke." (PMID 37298395, 2023).